ATP6V0A1 (ATPase H+ transporting V0 subunit a1)
Diseases named in the same sentence as ATP6V0A1 in open-access papers:
ATP6V0A1 is named in the same sentence as 44 diseases in open-access papers, as found by Europe PMC text mining. Sharing a sentence is not in itself a finding about the gene and the disease. The quoted sentences say what the papers report.
epilepsy (4 papers, 2021 to 2026). A brain disorder characterized by episodes of abnormally increased neuronal discharge resulting in transient episodes of sensory or motor neurological dysfunction, or psychic dysfunction. "Variants in ATP6V0A1, the brain-enriched isoform in the V0 domain, have been recently associated with developmental delay and epilepsy in four individuals." (PMID 34909687, 2021). "Our findings provide further support for considering OXC in the management of ATP6V0A1-related epilepsy." (PMID 42069687, 2026). "Many genes encoding subunits of V-ATPases, namely ATP6V0C, ATP6V1A, ATP6V0A1, and ATP6V1B2, have been associated with neurodevelopmental disorders and epilepsy." (PMID 37628590, 2023). "Here, we identify de novo and biallelic variants in ATP6V0A1, encoding the a1-subunit of the V0 domain, in individuals with DEE who showed various degrees of intellectual disability, developmental delay, and epilepsy." (PMID 33833240, 2021).
colorectal cancer (3 papers, 2024 to 2025). A primary or metastatic malignant neoplasm that affects the colon or rectum. "V-type proton ATPase 116 kDa subunit a 1 (ATP6V0A1) promotes cholesterol uptake in colorectal cancer cells by facilitating endosome maturation through rabaptin-5 GDP/GTP exchange factor (RABGEF1)." (PMID 40270603, 2025). "A recent study demonstrated that ATP6V0A1, a subunit of the V-ATPase (vacuolar ATPase) enzyme, facilitates cholesterol uptake in colorectal cancer cells to trigger immunosuppressive signals to inactivate memory CD8+ T cells." (PMID 39228987, 2024).
developmental and epileptic encephalopathies (2 papers, 2021 to 2023). "Recently, studies have reported that various de novo and biallelic mutations to ATP6V0A1 are a major cause of DEE (developmental and epileptic encephalopathies)." (PMID 37465367, 2023). "Recently reported, de novo and biallelic mutations of the human ATP6V0A1 impair autophagic and lysosomal activities, contributing to neuronal cell death in developmental and epileptic encephalopathies (DEE) and early onset progressive myoclonus epilepsy (PME)." (PMID 37465367, 2023).
neuroblastoma (2 papers, 2010 to 2021). Neuroblastoma (NB) is the most common solid, extracranial childhood tumor. "Notably, we compared the presence of the specific cassette exons in RNA from normal brain and neuroblastoma (for ATP6v0A1, STRADA, PCNP and CS) and from skeletal muscle and rhabdomyosarcoma (for TPM3, TPD52L2, NAP1L1, METT10 D and SLC25A3)." (PMID 20813049, 2010).
Obesity (2 papers, 2022 to 2024). Accumulation of substantial excess body fat. "Here the authors report that a vacuolar-type H+ ATPase, ATP6v0a1, is induced in adipocytes during obesity and persists after weight loss, and regulates food intake and weight gain in C. elegans and mice." (PMID 36042358, 2022). "In summary, using a series of genetic tools from invertebrates to vertebrates, we identify ATP6v0a1 as a regulator of peripheral metabolic memory, providing a potential target for regulation of food intake, weight loss maintenance and the treatment of obesity." (PMID 36042358, 2022). "Our data shows ATP6v0a1 expression is also elevated in genetic models of obesity and adipocytes from human individuals with obesity suggesting the effects are independent of diet composition." (PMID 36042358, 2022). "To test this hypothesis, we investigated the roles of ATP6V0A1 in exogenous lipid-induced CRC immune evasion using an MC38 tumor model in mice with obesity." (PMID 38971819, 2024). "Importantly, gene and protein expression of ATP6v0a1 is also increased in adipocytes from participants with obesity compared with lean controls and expression persists after weight loss in obese adipose tissue." (PMID 36042358, 2022). "Notably, in individuals with obesity, the adipocyte expression of ATP6v0a1 was higher compared with lean participants and expression levels do not decrease after weight loss." (PMID 36042358, 2022). "Thus, ATP6v0a1 is a target for future anti-obesity therapeutic strategies and the peripheral origin of this approach may reduce the likelihood of interfering with mental health than anti-obesity strategies that act directly on the brain." (PMID 36042358, 2022).
Brain atrophy (1 paper, 2021). Partial or complete wasting (loss) of brain tissue that was once present. "Brain MRI showed enlarged lateral ventricles in patient 1, and severe brain atrophy including cerebellum in individuals 3 and 4, suggesting that the cerebellum was commonly affected in the two individuals with biallelic ATP6V0A1 variants." (PMID 33833240, 2021).
colon cancer (1 paper, 2024). "To investigate the role of ATP6V0A1 in anti-tumor immunity in the context of human immune and colon cancer cells, we established a subcutaneous human colon cancer model in immunodeficient mice engrafted with human-derived immune cells." (PMID 38971819, 2024). "Collectively, these results indicate that tumor cell-intrinsic ATP6V0A1 suppresses anti-tumor immune responses and thus promotes tumor progression across different colon cancer models." (PMID 38971819, 2024). "Analysis of cell proliferation/tumor growth showed that ATP6V0A1 knockdown in human HCT8 colon cancer cells slightly (but significantly) increased their proliferation in vitro and in immune-deficient NCG mice but significantly suppressed their growth in immune-reconstituted huPBMC-NCG mice." (PMID 38971819, 2024).
cyst (1 paper, 2023). A sac-like closed membranous structure that may be empty or contain fluid or amorphous material. "N-glycosylated CELA3B (Asn-114, H5N4F1S0) and ATP6V0A1 (Asn-273, H5N4F0S1) were discarded from cyst fluid biomarkers due to their poor discriminative ability shown by PRM analysis." (PMID 37848412, 2023).
Epileptic encephalopathy (1 paper, 2021). A condition in which epileptiform abnormalities are believed to contribute to the progressive disturbance in cerebral function. "Here, the authors report that ATP6V0A1 variants identified in individuals with developmental and epileptic encephalopathy are associated with impairment of lysosomal acidification, autophagy and mTORC1 signaling, suggesting an essential role of ATP6V0A1 in brain development." (PMID 33833240, 2021).
glioblastoma (1 paper, 2010). The most malignant astrocytic tumor (WHO grade IV). "Of particular interest was the specific expression of ATP6v0A1, STRADA, PCNP and CS transcript variants, analyzed in patients affected by glioblastoma, which confirmed all the predicted cassette exons, thus demonstrating the reliability of our computational analysis." (PMID 20813049, 2010). "The validation of the cassette exons specific for the nervous system, detected for ATP6v0A1, STRADA, PCNP and CS genes, prompted us to analyze their expression in patients affected by glioblastoma, the most frequent form of primary intracranial malignancy." (PMID 20813049, 2010).
Granuloma (1 paper, 2022). A compact, organized collection of mature mononuclear phagocytes, which may be but is not necessarily accompanied by accessory features such as necrosis. "When compared to granuloma periphery or mucosa, CD68+ cells in the granulomata demonstrated increased gene expression in lysosome or macrophage-related genes such as CTSD, CD68, HEXB, ATP6V0A1, CTSK, LIPA, CD63." (PMID 36302964, 2022).
Lysosomal disease (1 paper, 2021). "We observed 11 missense mutations in ATP6V0A1, c.2219G>A recurring in 7 patients (6 of which are included in the present study), and concluded that ATP6V0A1 variants are the most common DNMs among all known lysosomal disease (LD) and LSD-associated genes in this database." (PMID 34909687, 2021).
nephropathic cystinosis (1 paper, 2025). An autosomal recessive condition caused by mutation(s) in the CTNS gene, encoding cystinosin. "We selected ATP6V0A1, the most downregulated v-ATPase, crucial for lysosomal acidification and investigated its association with the cystinosis phenotype." (PMID 40111391, 2025). "The novel findings are ATP6V0A1’s role in cystinosis-associated renal pathology and among other antioxidants, ATX specifically upregulated ATP6V0A1, improved autophagosome turnover or reduced autophagy and mitochondrial integrity." (PMID 40111391, 2025). "In summary, the novel findings of this study are ATP6V0A1’s role in cystinosis-associated renal pathology and, among other antioxidants, ATX specifically upregulated ATP6V0A1, improved autophagosome turnover, reduced autophagy, and secured mitochondrial integrity." (PMID 40111391, 2025). "ATP6V0A1 was significantly downregulated in cystinosis and highly co-regulated with loss of CTNS." (PMID 40111391, 2025). "We identified a list of vacuolar (v)-ATPases and ATP6V0A1 as the most downregulated genes in cystinotic RPTECs, which were also found to have a role in multiple cystinosis-related dysregulated pathways in our dataset." (PMID 40111391, 2025). "We are the first to show that ATX can induce the expression of ATP6V0A1 and has a protective effect against cystinosis-induced autophagosome formation and mitochondrial dysfunction." (PMID 40111391, 2025). "The most significantly perturbed member of the V-ATPase gene family that was found to be downregulated in cystinosis RPTECs is ATP6V0A1, hence further attention was focused on characterization of the role of this particular gene in a human in vitro model of cystinosis." (PMID 40111391, 2025). "Another notable finding of our study is the specific effect of antioxidant ATX on CTNS-/- RPTEC, which corrects the ATP6V0A1 levels, enhances autophagosomal turnover, improves cystinosis-induced mitochondrial dysfunction, and rescues mitochondrial membrane potential." (PMID 40111391, 2025). "We acknowledge that additional studies needed to understand the interplay between transcriptional regulations of ATP6V0A1 in cystinosis and if CTNS-/- cells, chronically treated with cysteamine, acquire any further changes to ATP6V0A1 expression." (PMID 40111391, 2025). "However, ATX was the only agent that upregulated ATP6V0A1 and provided recovery of the specific RPTEC injury phenotype in cystinosis." (PMID 40111391, 2025). "Astaxanthin (ATX) but not Cysteamine or Vitamin E upregulates ATP6V0A1 and rescued the cystinosis RPTEC phenotype." (PMID 40111391, 2025).
pancreatic ductal adenocarcinoma (1 paper, 2021). An infiltrating adenocarcinoma that arises from the epithelial cells of the pancreas. "ENST00000587299.1 and ENST00000553238.5 participated in the transcription of gene SLC8B1 and ATP6V0A1 that was associated with the invasive process of oral tongue cancer and pancreatic ductal adenocarcinoma, respectively." (PMID 34094912, 2021).
skin cancer (1 paper, 2020). "Additionally, the probe bafilomycin A1, the target of ATP6V0A1, showed the highest correlation coefficient (r = −0.999) in skin cancer." (PMID 32486001, 2020).
cancer (3 papers, 2022 to 2025). A tumor composed of atypical neoplastic, often pleomorphic cells that invade other tissues. "The top three genes with the highest AUC values (ORAI3, BCAM, and ATP6V0A1) have been associated with cancer development." (PMID 38256136, 2024). "In addition, 1 SNP was detected in KMT2C, a BC oncogene, and 9 others were detected in or near 10 genes (SERAC1, DAGLB, MACF1, NVL, FBXW4, FANK1, KCTD4, CAVIN1; ATP6V0A1 and ZBTB20-AS1) previously associated with non-BC cancers." (PMID 35589867, 2022).
neurodevelopmental disorder (3 papers, 2021 to 2023). A behavioral and cognitive disorder with onset during the developmental period that involves impaired or aberrant development of intellectual, motor, or social functions. "Overall, recent findings on ATP6V0A1 mutations in neurodevelopmental disorders emphasize the paramount role of V-ATPases in the development and maintenance of proper lysosomal and autophagosomal activity." (PMID 37465367, 2023). "Therefore, it is postulated that various degrees of impairment of ATP6V0A1 function with both dominant and recessive inheritance are associated with neurodevelopmental disorders." (PMID 33833240, 2021). "In this study, we identified de novo and biallelic ATP6V0A1 variants in four individuals with DEE, suggesting that various degrees of impairment of ATP6V0A1 function are associated with neurodevelopmental disorders." (PMID 33833240, 2021).
tumor (3 papers, 2024 to 2025). "The alterations in tumor growth caused by either ATP6V0A1 depletion or overexpression were completely abolished or significantly reduced in immunodeficient Rag2−/−Il2rg−/− or NOD/SCID mice." (PMID 38971819, 2024). "Decreased expression in DCIS was observed for ATP6V0A1, which plays a role in pH homeostasis and tumor cell invasion." (PMID 39723668, 2025). "We went on to further confirm the contribution of TGF-β1 to Atp6v0a1-mediated regulation of tumor immune evasion in vivo." (PMID 38971819, 2024). "On the other hand, both RABGEF1 and TGF-β1 were rarely detected in the tumor tissues with minimal detection of ATP6V0A1 (lower)." (PMID 38971819, 2024). "Our findings reveal a novel function of ATP6V0A1 in facilitating tumor progression by inhibiting anti-tumor immune response." (PMID 38971819, 2024). "Here, we show that tumor cell-intrinsic ATP6V0A1 drives exogenous cholesterol-induced immunosuppression in CRC." (PMID 38971819, 2024). "Collectively, our data suggest that the TGF-β1/SMAD3 axis is critical for the regulation of the anti-tumor activities of CD44+CD8+ T cells by CRC cell-expressed ATP6V0A1." (PMID 38971819, 2024). "Subsequently, we employed these modified cells to investigate the impact of tumor cell-intrinsic ATP6V0A1 on suppressing anti-tumor immunity in syngeneic and xenograft mouse models of CRC." (PMID 38971819, 2024). "Collectively, ATP6V0A1 is highly expressed in human CRCs and predicts inactive anti-tumor immunity and poor survival." (PMID 38971819, 2024). "Our results suggested that tumor-intrinsic ATP6V0A1 induces immunosuppressive signaling and immune evasion in CRC by decreasing the effectiveness of memory CD8+ T cells." (PMID 38971819, 2024). "Collectively, these data suggest that ATP6V0A1 expressed in CRC tumor cells promotes immune evasion mainly by suppressing the effectiveness of memory CD8+ T cells." (PMID 38971819, 2024). "Here, the authors show that tumor cell-intrinsic ATP6V0A1 drives RABGEF1-dependent cholesterol absorption and thus triggers paracrine TGF-β1/SMAD3 signaling to inactive memory CD8+ T cells in CRC." (PMID 38971819, 2024). "Moreover, the IHC analysis of CRC samples also revealed an elevated expression level of ATP6V0A1 in the tumor niches compared to the stromal areas." (PMID 38971819, 2024). "We also found that ATP6V0A1 is highly expressed in tumor cells and fibroblasts of NB tissues." (PMID 39228987, 2024). "Importantly, the levels of cytotoxic cytokines in CD44+CD8+ T cells were also significantly enhanced in the orthotopic (cecal) MC38 tumor model as a result of Atp6v0a1 knockdown." (PMID 38971819, 2024). "Importantly, inhibition of ATP6V0A1 by expression interference or inhibitor treatment was shown to suppress tumor growth and restore anti-tumor immunity in both dMMR and pMMR murine CRCs." (PMID 38971819, 2024). "Importantly, we revealed tumor cell-intrinsic ATP6V0A1 as a novel immunosuppressive factor that promotes RABGEF1-dependent cholesterol absorption in CRC cells, consequently initiating paracrine TGF-β1/SMAD3 signaling to deactivate memory CD8+ T cells." (PMID 38971819, 2024). "Next, to test whether tumor cell-intrinsic ATP6V0A1 could promote the development of orthotopic CRCs, we established a cecal MC38 tumor model." (PMID 38971819, 2024). "We initially evaluated the expression level of ATP6V0A1 in CRC tumor cells." (PMID 38971819, 2024). "Moreover, significant colocalization of ATP6V0A1 and RABGEF1 or TGF-β1 was observed in the tumor tissues with high ATP6V0A1." (PMID 38971819, 2024). "Moreover, we identify daclatasvir, a clinically used anti-hepatitis C virus (HCV) drug, as an ATP6V0A1 inhibitor that can effectively enhance the memory CD8+ T cell activity and suppress tumor growth in CRC." (PMID 38971819, 2024). "Additionally, a higher expression rate of IFN-γ in CD45RO+ memory CD8+ T cells was observed in the tumor tissues with low ATP6V0A1 rather than those with high ATP6V0A1." (PMID 38971819, 2024).
tumor (continued). "Moreover, the restoration of Tgfb1 expression in MC38 tumor cells had a comparable impact to exogenous TGF-β1 in mitigating the tumor suppression and CD44+CD8+ T cell activation induced by Atp6v0a1 depletion." (PMID 38971819, 2024). "According to the immunohistochemical (IHC) analysis of a human CRC tissue microarray, ATP6V0A1 exhibited significantly higher expression levels in tumor tissues compared to adjacent non-tumor tissues (paired t-test; p < 0.0001), regardless of dMMR and pMMR status." (PMID 38971819, 2024). "Notably, in CRC, the therapeutic effect of anti-TGF-β1 may not replace that of targeting ATP6V0A1 since anti-TGF-β1 treatment only partially weakened the promoting effect of Atp6v0a1 overexpression on MC38 tumor growth." (PMID 38971819, 2024). "Within the tumor tissues with ATP6V0A1 expression, both expression of RABGEF1 and TGF-β1 were relatively higher in the areas with high ATP6V0A1 rather than those with low ATP6V0A1 (upper)." (PMID 38971819, 2024). "Finally, Dac treatment suppressed the tumor growth and restored the activation of CD44+CD8+ T cells in control MC38 tumors but not in ATP6V0A1-suppressing MC38 tumors." (PMID 38971819, 2024).
infection (2 papers, 2013 to 2025). The state of being infected such as from the introduction of a foreign agent such as serum, vaccine, antigenic substance or organism. "Western blot analyses revealed that the levels of VO subunits ATP6V0A1, ATP6V0A2, ATP6V0A3, and ATP6V0C were significantly decreased in the floxed MEFs after Ad-Cre infection, but V1 subunit ATP6V1E2 was unaffected." (PMID 24223829, 2013).
movement disorder (1 paper, 2025). Neurological conditions resulting in abnormal voluntary or involuntary movement, which may impact the speed, fluency, quality and ease of movement. "Rescued XDP signature genes such as GABRA5, STX6, and ATP6V0A1 code for subunits of channels or receptors that map to glutamatergic or GABAergic synapses, cellular components that are relevant for neurotransmission and the movement disorder phenotype observed in XDP." (PMID 41282719, 2025).
neurodegenerative disease (1 paper, 2020). A disorder of the central nervous system characterized by gradual and progressive loss of neural tissue and neurologic function. "The relevance of Atp6v0a1 disruption to neurodegenerative diseases is not clear." (PMID 33006978, 2020).
neurological disorders (1 paper, 2023). "Recently, two groups of researchers identified de novo and biallelic variants of ATP6V0A1, encoding the a1 subunit, in individuals with rare neurological disorders: DEE and early onset PME." (PMID 37465367, 2023).
ATP6V0A1 also shares sentences with these, for which no sentence is quoted: Intellectual disability (2 papers); major depression (2); progressive myoclonus epilepsy (2); schizophrenia (2); Ataxia (1); cardiovascular diseases (1); Cirrhosis (1); developmental and epileptic encephalopathy 104 (1); developmental delays (1); glaucoma (1); hepatitis C virus (1); Hypertension (1); microcephaly (1); nephrocalcinosis (1); nephrolithiasis (1); oligoastrocytoma (1); oligodendroglioma (1); psychiatric disorder (1); renal carcinoma (1); Rett-like syndrome (1); rhabdomyosarcoma (1); rheumatoid arthritis (1).